IL1B (interleukin 1 beta)
Diseases named in the same sentence as IL1B in open-access papers (continued):
Sharing a sentence is not in itself a finding about the gene and the disease.
osteoporosis (continued). "Activation of NF-κB plays an important role in the pathogenesis of osteoporosis by the upregulation of TNF-α, IL-1β, ICAM-1, iNOS, and COX-2 expressions." (PMID 24348690, 2013). "Our results for the significantly high IL-1β and TNF-α levels observed in the OVX rats could suggest that olive oil may have an anti-inflammatory effect in OVX-induced osteoporosis." (PMID 40125318, 2025). "In this study, the downregulation of IL-6, TNF-α, IL-1β, MMP3, MMP9, and caspase-3 by curculigoside aligns with previous findings that these factors mediate osteoblast injury and extracellular matrix degradation in osteoporosis." (PMID 40917365, 2025). "Hence, the immune microenvironment, comprising immune cells and inflammatory factors (IL-1β, IL-18, IL-17, IL-6, and TNF-α), plays a pivotal regulatory role in bone metabolism and contributes to the pathogenesis of osteoporosis." (PMID 38895114, 2024). "Therefore, the IL1B and NF-κB (RelA and NFKB1) signaling pathways are key targets to treat osteoporosis phenotypes." (PMID 35888070, 2022). "In vitro stimulation of whole blood cells harvested from postmenopausal osteoporosis patients produced higher levels of IL-1β, IL-6, TNF-α, IFN-γ, and GM-CSF compared to healthy controls, and IL-1β levels were negatively correlated with lumbar spine (L2-4) bone mineral density in patients." (PMID 35567665, 2022). "Indeed, pyroptosis participates in the pathogenesis of osteoporosis mainly via activating NLRP3 and secreting mature IL-1β and IL-18, which will be demonstrated as follows." (PMID 33488513, 2020). "The study aims to evaluate the associations between proinflammatory markers (IL-1β, IL-6, and TNF-α) with BTMs in postmenopausal Saudi women with and without osteoporosis." (PMID 28121926, 2017). "A significant negative correlation between osteocalcin and IL-1β in healthy women and women with osteoporosis were observed." (PMID 28121926, 2017). "IL-1β and other proinflammatory cytokines are increased in patients with SLE and they may further contribute to the development of osteoporosis." (PMID 25954061, 2015). "IL-1β, IL-6, TNF-α, and the osteoporosis-related protein system OPG/RANK/RANKL may have some synergetic effects on emphysema and bone loss in COPD." (PMID 22176920, 2011). "Experimental studies indicate that IL-1β, IL-6 and TNF-α may play important roles in the etiology of both osteoporosis and emphysema." (PMID 22176920, 2011). "Marrow fat secretes several adipokines, such as Leptin, Adiponectin, TNFα, IL1β, and IL6, which promote chronic inflammatory responses and are shown to be highly correlated with bone cancer metastasis and markers for the progression of bone diseases such as osteoporosis." (PMID 39056808, 2024). "A study involving 45 postmenopausal women showed that the circulating levels of IL-1β, IL-6, and TNF-α in postmenopausal women with osteoporosis were significantly higher than those without osteoporosis." (PMID 37035758, 2023). "The mean values of the serums of IL-1β, IL-6 and TNF-α in the osteoporosis group were significantly higher than those in the non-osteoporosis group (P < 0.05)." (PMID 37038178, 2023). "We studied the IL-1α (-889C/T), IL-1β (-511C/T) and the 86 base pair variable number tandem repeat (VNTR) in intron 2 of the IL-1 receptor antagonist (IL-1ra) gene in 117 postmenopausal women with osteoporosis and 135 control subjects without a history of symptomatic osteoporosis." (PMID 20940514, 2010).
Salmonella Infections (90 papers, 2010 to 2026). Infections with bacteria of the genus SALMONELLA. "To understand how IL-1β deficiency affects the colonic tissue during Salmonella infection, we performed bulk RNA sequencing followed by pathway analysis of differentially expressed genes." (PMID 38236896, 2024). "Salmonella infection changes the gut barrier and immune system by causing the production of cytokines such as interleukin-1 (IL-1β), interleukin-8 (IL-8), interleukin-6 (IL-6), lipopolysaccharide-induced tumor necrosis factor (LITAF), and interferon-(IFN-γ)." (PMID 34944274, 2021). "Mice deficient in IL-1β succumb more easily to Salmonella infection, highlighting the importance of this cytokine in the mucosal immune response against this pathogen." (PMID 33292444, 2020). "We then tested whether loss of IL-1β leads to reduced neutrophils levels during Salmonella infection because of neutrophil development defects, or failure to recruit neutrophils to the colonic tissue." (PMID 38236896, 2024). "(C–E) RT-qPCR analysis of mRNAs encoding inflammatory cytokines (Tnfα, Il1β, and Il6), chemokines (Ccr2, Ccl2, Cxcl1, and Cxcl10) and macrophage biomarkers (Nos2 and Arg1) in BMDMs measured at the indicated times after Salmonella infection (multiplicity of infection [MOI] = 1) (n = 5)." (PMID 39475776, 2024). "IL-1β deficiency increases both severity and mortality rate associated with Salmonella infection." (PMID 34061266, 2021). "In fact, Pkcδ deficiency enhanced IL-1β secretion in response to Shigella and Salmonella infection." (PMID 24516390, 2014). "Induction of pro-inflammatory cytokines, such as tumor necrosis factor-alpha (TNF-α) and interleukin-1 beta (IL-1β), following Salmonella infection in tumor-bearing hosts is indicative of host-mediated tumoricidal effects." (PMID 39873483, 2025). "The Salmonella infection significantly altered mRNA levels of pro-inflammatory cytokines (IL-6, IL-1α, IL-1β, and TNF-α)." (PMID 38667028, 2024). "During enteric Salmonella infection, the activation of caspase-1 and the production of IL-1β and IL-18 provide a protective host response." (PMID 38396532, 2024). "Salmonella infection boosts assembly and function of the inflammasome, a protein complex that modifies precursors of the inflammatory cytokines, IL-1β and IL-18, driving pyroptosis." (PMID 39697327, 2024). "Accordingly, we found that the colonocytes in IL-1β-/- mice remained hypoxic during Salmonella infection while colons of WT mice became rich in oxygen." (PMID 38236896, 2024). "We found that IL-1β-/- mice express 4-fold higher transcription levels of Cpn1 after Salmonella infection, compared with WT mice." (PMID 38236896, 2024). "16S rRNA microbiota analysis of feces from infected WT and IL-1β-/- mice revealed that the latter contained a more diverse microbiota after Salmonella infection." (PMID 38236896, 2024). "Further, in some situations, such as during acute Salmonella infection, neutrophils can escape cell death and maintain IL-1β production by activating the NLRC4 inflammasome." (PMID 39697327, 2024). "Salmonella infection triggers the release of cytokines such as IL-6, IL-1β and TNF-α, resulting in systemic inflammatory stress." (PMID 38715123, 2024). "Salmonella infection significantly increased the ileal contents of inflammatory cytokines (IL-1β, IL-6, IL-8, TNF-α, IFN-β and IFN-γ) compared with the CON." (PMID 36670458, 2023). "A previous study showed that Salmonella infection increased contents of IL-1β, IL-8, IFN-β, and IFN-γ in plasma of chickens." (PMID 36670458, 2023). "Salmonella infection in chickens increases the serum concentrations of IgG and IgA and IL-1β, IL-6, and TNF-α." (PMID 38053560, 2023). "Salmonella infection increased the expression of IL-1β, IL-6, and TNF-α in the jejunal and ileal mucosa of broilers." (PMID 38053560, 2023).
Salmonella Infections (continued). "The results revealed that SMI-4a had the inhibitory effect on AIM2 inflammasome and NLRC4 inflammasome, trigged by poly (dA:dT) transfection or Salmonella infection, resulting in a decrease in IL-1β production." (PMID 37422640, 2023). "CARD9 upregulates IL-1β production in fungal infection, whereas it negatively regulates the NLRP3 inflammasome-induced IL-1β production in BMDMs in response to Salmonella infection." (PMID 35173530, 2022). "The pharmacological inhibition of PI3K or Akt, as well as the deletion of the rictor gene in B cells, is capable of rescuing the transcription of NLRP4 and IL-1β production, reflecting the control of Salmonella infection." (PMID 35805144, 2022). "In contrast, other studies reported an increase in IL-1β and IL-8 during the days following Salmonella infection." (PMID 34944274, 2021). "Since Il-1β signalling is important for control of Salmonella infection in the intestine and Il1rap is necessary for formation of a functional Il1 receptor, we intend to assess the physiological effect of SteD on Il1rap in future studies." (PMID 34314469, 2021). "Similar to the present findings, CARD9−/− mice exhibit increased splenic IL-1β expressions following systemic Salmonella infection." (PMID 34209576, 2021). "After Salmonella infection, three immune-related traits were measured to assess the immune response, including IL-1β, IL-8 expression, IgA production, and bacterial loads." (PMID 32075044, 2020). "It has also been reported that Salmonella infection increased the levels of IL-6, IL-8, and IL-1β in the colons of pigs." (PMID 32150574, 2020). "It has been reported that Salmonella infection enhanced the levels of proinflammatory cytokines IL-1β, IL-8, and LITNF." (PMID 32528455, 2020). "IL-1β is involved in protection against Salmonella infection by limiting its entry into systemic sites." (PMID 32545295, 2020). "Interleukin related (il1b) and chemokine ligand 8a (cxcl8a) gene expression was upregulated by site H1, which were enriched in salmonella infection pathway." (PMID 30081495, 2018). "CCL20 expression can be promoted by producing the proinflammatory cytokines TNF-α and IL-1β during Salmonella infection." (PMID 28770173, 2017). "It was reported that Salmonella infection stimulated pyroptosis of macrophages, a newly identified program of caspase-1-correlated cellular demise, resulting in cell lysis with release of IL-1β and IL-18." (PMID 26811498, 2016). "We then hypothesized that the reason for resistance to Salmonella infection in IL-1β-/- mice is that they can clear the infection." (PMID 38236896, 2024). "We next tested whether changes in the gut microbiota of IL-1β-/- mice can explain their resistance to Salmonella infection." (PMID 38236896, 2024). "However, we found that vancomycin-treated IL-1β-/- mice still survived after oral Salmonella infection." (PMID 38236896, 2024). "Here, we set out to determine whether host production of IL-1β is protective during Salmonella infection and discovered that the pathogen exploits this cytokine to drive pathogenicity." (PMID 38236896, 2024). "Here, we show that IL-1β production is detrimental during Salmonella infection." (PMID 38236896, 2024). "To date, the effect of Salmonella infection and proinflammatory cytokine IL-1β on the intestinal uptake of ascorbic acid (AA) is unknown." (PMID 36704315, 2023). "In addition, the Casp1-/—, IL-1β-/—, and IL-18-/—mice also succumbed to Salmonella infection more rapidly than wild-type (WT)-C57BL/6 mice, with markedly higher bacterial burdens in spleens, Peyer’s patches, and mesenteric lymph nodes." (PMID 37155697, 2023). "Therefore, when the intestinal barrier function is destroyed upon salmonella infection, these pro-inflammatory cytokines, including IL-1β, IL-6, IL-8, IFN, and TNF-α, are activated." (PMID 35371085, 2022).
Salmonella Infections (continued). "Our results led us to hypothesize a role for neutrophil IL1-β in the PMN-HIOs as a crucial signal for effective epithelial cell shedding during Salmonella infection." (PMID 36191054, 2022). "Likewise, B lymphocytes from rictor gene conditional knockout mice also produce IL-1β and efficiently control Salmonella infection." (PMID 35805144, 2022). "Importantly, serum IL-1β, which was dramatically increased in iron-loaded FthΔ/Δ mice in Salmonella infection, was barely altered in the setting of LPS challenge." (PMID 34236052, 2021). "Furthermore, IL-1β inoculation decreases Salmonella-infected mice’s mortality, while the neutralization or inhibition of IL-1β production increases the severity of Salmonella infection, reducing the host survival rate." (PMID 34944274, 2021). "Additionally, Clock deficient BMDMs exhibit reduced expression of proinflammatory genes Il-6, Il1b, Tnfα, Ifn-β, and Ccl2 upon LPS stimulation and decreased secretion of IL-6 and IL-1β after Salmonella infection." (PMID 34595127, 2021). "During invasive Salmonella infection, pattern recognition receptors initiate the innate immune system leading to the recruitment of neutrophils and macrophages and the production of proinflammatory cytokines (IL-6, IL-1β) to promote pathogen clearance." (PMID 32842467, 2020). "In this study, we have shown that SLAMF9‐deficient mice have impaired clearance of systemic Salmonella infection, and suppression of SLAMF9 expression in human THP‐1 cells dramatically reduces their ability to produce pro‐inflammatory cytokines TNF‐α, IL‐1β and GM‐CSF." (PMID 31880316, 2020). "Notably, the Pkcδ kinase was dispensable for caspase-1 activation and secretion of IL-1β induced by Shigella or Salmonella infection." (PMID 24516390, 2014). "The model predicts that Casp11 induced cell death in the absence of Casp1-dependent IL-1B and IL-18 production increases host susceptibility to Salmonella infection." (PMID 23977202, 2013). "The activation of IL-1β during Salmonella infection is a complex process employing several different pathways, and it is difficult to discern the contribution of each process to the net systemic concentration of IL-1β." (PMID 26904722, 2013). "IL-1β mRNA synthesis is increased in intestinal epithelial cells after Salmonella infection." (PMID 20529359, 2010). "Thus, IL-1β drives expression of anaphylatoxin proteins and receptors during Salmonella infection." (PMID 38236896, 2024). "However, Salmonella infection of macrophages still activates caspase-1 and induces IL-1β release." (PMID 22563421, 2012). "It has been established that during early Salmonella infection, inflammatory monocytes produce anti-microbial factors such as TNF-α and IL-1β." (PMID 40014608, 2025). "Both wild-type and knockout chickens showed significant upregulation of pro-inflammatory cytokines after Salmonella infection, including IFN-γ, IL-1β, IL-22, LITAF, and the chemokine K203, compared to their mock-infected controls." (PMID 40438105, 2025). "Compared with CON, plasma concentrations of IFN-β IL-8 (P < 0.01), IgG, IgA, IL-1β, TNF-α, and IFN-γ (P < 0.05) increased following Salmonella infection (SI)." (PMID 38053560, 2023). "Salmonella infection promotes the expression of inflammasome NLRP3, leading to activation and release of proinflammatory cytokines such as IL-1β, and the infected host often displays altered nutrient levels." (PMID 36704315, 2023). "In the context of Salmonella infection, it has also been reported that CARD9 negatively regulates IL-1β by fine-tuning pro-IL-1β expression, SYK-mediated NLRP3 activation and repressing inflammasome-associated caspase-8 activity." (PMID 37528097, 2023). "A previous study reported that a number of cytokines, including IL-1β and TNF-α, are produced during the initial salmonella infection." (PMID 35371085, 2022).
Salmonella Infections (continued). "Salmonella infection triggers a signal for the expression of a diverse range of inflammatory cytokines, such as TNF-α, IL-1β, and IFN-γ." (PMID 36183131, 2022). "There had been an interaction between heat stress and Salmonella infection in the expressions of TNF-α, IL-6, IL-1β, pro-IL-1β, and NLRP3." (PMID 34061266, 2021). "The host anti-tumor responses can be induced after Salmonella infection by recruiting immune cells, such as neutrophils, macrophages, dendritic cells and CD8+ T cells, and cytokines including IL-1β and TNF-α into tumor tissue." (PMID 35003007, 2021). "Many studies have indicated that the expression of proinflammatory cytokines such as IFN-γ, IL-6, IL-1β, LITAF, and anti-inflammatory cytokines (IL-10 and transforming growth factor-β4) is regulated in the cecal tonsils by Salmonella infection." (PMID 32054193, 2020). "Similar to the findings of previous reports, GA treatment inhibited caspase-1 activation, IL-1β maturation and ASC oligomerization triggered by nigericin, cytosolic LPS or Salmonella infection, aside from poly(dA:dT) transfection." (PMID 32312957, 2020). "Despite altered bacterial clearance, control macrophages and butyrate macrophages displayed similar expression of IL1B and TNF mRNA and protein following 3 h of Salmonella infection, whereas IL10 expression was reduced in butyrate macrophages." (PMID 30683619, 2019). "Salmonella infection (SAL group) significantly increased the levels of LITAF, IL-1β, and IL-6 in serum compared with the NC group (P < 0.05)." (PMID 29396554, 2018). "Instead, genes such as IL1β, IL6 or both chicken orthologues of IL8 (EMF-1 and K60), which are commonly used as markers of inflammation following Salmonella infection of chickens were inducible also in fibroblasts." (PMID 26046914, 2015). "Furthermore, by functional studies we demonstrated that UCH-L5, which activity is up-regulated in the host during Salmonella infection, might constitute an important pro-inflammatory deubiquitinase, which leads to an increased inflammasome activation and regulates secretion of IL-1β." (PMID 26267804, 2015). "Compared to the CON, clove extract and eugenol notably reduced the expression levels of pro-inflammatory cytokines IL-1β, IL-6, and TNF-α in the jejunal tissue and crypts of yellow feather broilers; Salmonella infection significantly elevated the levels of these inflammatory factors." (PMID 40059168, 2025). "This capability of different pathways to drive IL-1β secretion can also explain why mice deficient in individual components of the inflammasome have not shown the same resistance to Salmonella infection as we show here in IL-1β-/- mice." (PMID 38236896, 2024). "To understand why IL-1β-/- mice do not die from Salmonella infection, we performed RNA sequencing on mice 6 d.p.i., as this is the time point when WT mice are moribund." (PMID 38236896, 2024). "In THP-1 macrophages, GSDME mediates IL-1β release and limited pyroptosis in response to nigericin treatment and Salmonella infection, as well as pyroptosis in the absence of GSDMD." (PMID 37279255, 2023). "In this work, we observed a strong correlation of the H/L ratio with IL-1β and IFN-γ intestinal expression, indicating that the H/L ratio can be used as a blood indicator to select and predict the Salmonella infection resistance also to predict the intestinal immunity level in vivo in chickens." (PMID 34944274, 2021). "During acute Salmonella infection, neutrophils can activate the NLRC4 inflammasome to produce IL-1β, without undergoing pyroptosis, and thus they can continue their inflammasome-independent antimicrobial effector functions while maintaining IL-1β secretion." (PMID 33746968, 2021). "The secretion of the strictly inflammasome-dependent IL-1β (see the results of costimulation with AC-YVAD-cmk) was further strongly augmented by a short-time 3-hour Salmonella infection in those cells and was dramatically higher in the KO than in WT macrophages." (PMID 34236052, 2021).